NCF1 (neutrophil cytosolic factor 1)
Diseases named in the same sentence as NCF1 in open-access papers (continued):
Sharing a sentence is not in itself a finding about the gene and the disease.
melanoma (13 papers, 2013 to 2025). A malignant, usually aggressive tumor composed of atypical, neoplastic melanocytes. "A natural mutation in the Ncf1 gene leading to an impaired production of ROS by the NOX2 complex protects against B16 melanoma tumor colonization of the lungs." (PMID 34257370, 2021). "gp91phox, Ncf1 (p47phox), and Rac2-deficient mice all exhibit fewer lung metastases than control mice in experimental melanoma models." (PMID 28351984, 2017). "In another case, the low expression of NCF1 was associated with poor survival rates in melanoma patients (P = 0.04)." (PMID 25360158, 2014). "Ncf1 deficiency leads to accumulation of anti-tumor immune cells, which may mediate the molecular mechanism of reduced melanoma lung metastasis." (PMID 37274231, 2023). "Mice deficient in NCF1 exhibit reduced melanoma growth and metastasis." (PMID 37274231, 2023). "NCF1 overexpression has been linked to melanoma lung metastases and colonization." (PMID 37274231, 2023). "NCF1 encodes a protein that is one of the subunits of NADPH oxidase, and inhibition of NCF1 induces differentiation of APL cells as well as inhibits melanoma cell growth." (PMID 38799454, 2024). "To study a possible tumor protection effect by the Ncf1 mutation in a manner dependent on cell types, we used experimental mouse models of lung colonization assay by B16F10 melanoma cells." (PMID 34257370, 2021). "We have now chosen the shared melanoma model B16F10 cell line, supplied by ATCC, to probe the mechanisms of cell-specific Ncf1 mutations in tumor colonization." (PMID 34257370, 2021). "Using the MHC congenic mice in the mouse melanoma model, we observed a reduced number of lung colonies in Ncf1 mutant mice." (PMID 34257370, 2021). "In contrast to the findings presented here, the growth of the transplantable mouse B16 melanoma and the Lewis lung carcinoma was, when tested in the same NCF1 mutant model, found to be significantly enhanced by NOX2 complex derived ROS." (PMID 26076008, 2015). "Using a statistical framework, we identified four putative cancer genes (RWDD1, NCF1, PLEK, and VAV3), whose expression profiles were associated with overall poor survival rates in melanoma, lung, or colorectal cancer patients." (PMID 25360158, 2014). "We identified four putative cancer genes (RWDD1, NCF1, PLEK, and VAV3), whose gene expression profiles were associated with overall poor survival rates in melanoma, lung, or colorectal cancer patients." (PMID 25360158, 2014). "To demonstrate the potential value of our approach, we identified four putative cancer genes (RWDD1, NCF1, PLEK, and VAV3), whose expression was associated with poor survival rates in melanoma, lung, or colon cancer patients." (PMID 25360158, 2014). "Building from our approach, we identified four new putative cancer genes (RWDD1, NCF1, PLEK, and VAV3), whose expression profiles were found to be associated with poor survival rates in melanoma, lung, or colon cancer patients." (PMID 25360158, 2014). "Ncf1 promotes metastatic colonization of melanoma tumors via ROS." (PMID 37274231, 2023). "Collectively, RWDD1 and NCF1 are two putative candidate targets for melanoma treatment." (PMID 25360158, 2014). "While many cancers display oxidative stress as a result of mitochondrial dysfunctions some types of prostate carcinomas and melanoma have been found to over-express NOX2, leading us to evaluate whether the tumor cell lines produced amounts of oxidative stress related to their NCF1 mutation status." (PMID 26076008, 2015). "We and others have found that impaired NCF1 and NOX2 function are protective against the melanoma development." (PMID 34257370, 2021).
Immunodeficiency (11 papers, 2012 to 2025). Failure of the immune system to protect the body adequately from infection, due to the absence or insufficiency of some component process or substance. "The severe immunodeficiency caused by NCF1 defects translates into most CGD patients being diagnosed at an early age." (PMID 40710296, 2025). "NCF1 deficiency will lead to the reduction of ROS, which is associated with immune disorders." (PMID 35923697, 2022). "Additionally, due to genetic variants, deletions of NCF1, NCF2, and CYBB can cause hereditary immune diseases." (PMID 36718447, 2023). "NCF1 encodes a component of neutrophil NADPH oxidase, which when mutated causes an immunodeficiency condition with no overt neurological phenotype." (PMID 23118870, 2012).
liver fibrosis (10 papers, 2013 to 2025). "NCF1- derived ROS play an important role in liver fibrosis and loss of NCF1 function in mice results in resistant to liver fibrosis." (PMID 33281601, 2020). "In addition, SRF promotes liver fibrosis by inducing the transcriptional activation of NCF1/NCF2 to promote ROS production." (PMID 40045169, 2025).
Sepsis (10 papers, 2012 to 2021). Sepsis is defined as life-threatening organ dysfunction caused by a dysregulated host response to infection. "Septicemia due to C. violaceum has also been documented in a child with NCF1 defect who hailed from Central India." (PMID 33717137, 2021).
diabetic nephropathy (8 papers, 2011 to 2025). "NCF1, OSM, SMAD1 and TGFB1 provide protection against diabetic nephropathy, SYVM1 and TXNIP protect against diabetic retinopathy and BDNF in ameliorating the diabetic neuropathy." (PMID 28761062, 2017).
colon cancer (7 papers, 2014 to 2025). "Exogenous NCF1 overexpression in colon cancer cells increases oxidant production and nuclear ABL phosphorylation, leading to apoptosis." (PMID 39354505, 2024). "We performed bioinformatic analysis to assess the gene expression of NCF4, NCF1, and NCF2 in colon tumors and control tissues from 480 colorectal cancer (CRC) patients and 41 paired tumors and associated normal tissues available in the TCGA database." (PMID 38886341, 2024). "Murine knockout of neutrophil cytosolic factor 1 (NCF1/p47phox), an adaptor protein involved in nicotinamide adenine dinucleotide phosphate (NADPH) oxidase activation, protects mice from colon cancer." (PMID 39354505, 2024). "Combining the expression trends of these genes in colon cancer and after aspirin treatment, we found that aspirin further upregulated NOX4, CXCL8, CXCL5, LIF, GDF15, and MMP13, while stimulated inhibition of IL2, NCF1, and PTGS1." (PMID 41425852, 2025).
Granuloma (7 papers, 2005 to 2026). A compact, organized collection of mature mononuclear phagocytes, which may be but is not necessarily accompanied by accessory features such as necrosis. "Within mycobacteria-induced granulomas there is an oxidative environment, which is completely abolished in Ncf1 mutant mice demonstrating that NOX2 is the source of oxidative stress." (PMID 25188296, 2014). "BCG-induced granulomas in Ncf1 mutant mice were larger, but of atypical appearance: acidophilic centers were not detectable; numerous neutrophils were infiltrated; and the delimitation of granuloma boarders was barely perceivable." (PMID 25188296, 2014). "To characterize the differences in granulomatous inflammation between Ncf1-/- mice and WT mice, we used immunohistochemical stain to identify macrophages (F4/80 staining) given that macrophages are the essential cells of mycobacterium-induced granulomas." (PMID 29228045, 2017). "In preclinical studies, lentiviral delivery of functional NCF1 restored ROS in CGD patient neutrophils and reduced infection rates and granuloma size." (PMID 40710296, 2025). "Here, we show that Cyba−/− mice spontaneously develop granuloma and, therefore, constitute a CGD animal model to complement the existing Cybb−/− and Ncf1−/− models." (PMID 34445407, 2021).
psoriasis (7 papers, 2014 to 2025). An autoimmune condition characterized by red, well-delineated plaques with silvery scales that are usually on the extensor surfaces and scalp. "We show that the human Ncf1-339 polymorphism (NCF190H variant) is associated with mouse psoriasis, confirmed by mannan-induced PsA and PsO mouse models." (PMID 37507888, 2023). "The susceptibility to psoriasis-like inflammation induced by mannan in mice is regulated by ROS from the NCF1/NOX2 complex." (PMID 37507888, 2023). "The NCF190H variant aggravates mouse psoriasis through hyperactivated macrophages with high NCF1 expression, expanded keratinocytes, upregulated IL-23/IL-17 axis, and JAK-STAT signaling pathway." (PMID 37507888, 2023). "Mannan-induced psoriasis was significantly ameliorated by the 1,6-β-glucan in Ncf1-mutated mice." (PMID 35551269, 2022). "To investigate the role of the human NCF190H variant in mouse psoriasis in a NOX2-derived ROS-dependent way, we knocked in the R90H variant in the Ncf1 gene by CRISPR/Cas9 in B6N ES cells and backcrossed to C57BL/6N.Q mice." (PMID 37507888, 2023). "To summarize, a defined SNP (NCF1-339, also named NCF190H) was found to activate the IL-23/IL-17 axis and JAK-STAT signaling pathways, leading to hyperactivation of macrophages and keratinocytes and causing mouse psoriasis and psoriatic arthritis." (PMID 37507888, 2023). "Mice with a mutation in Ncf1 leading to a functionally deficient NCF1, but not the mutation of NCF4, regulate MIP, indicating that the NOX2 complex regulates psoriasis and autoimmune arthritis differentially." (PMID 37507888, 2023).
experimental autoimmune encephalomyelitis (5 papers, 2008 to 2022). An autoimmune demyelinating disease of the central nervous system that is produced experimentally in animals by the injection of homogenized brain or spinal cord in Freund's adjuvant. "Increasing evidence has suggested that a single nucleotide polymorphism in the Ncf1 gene is associated with experimental autoimmune encephalomyelitis (EAE)." (PMID 32276661, 2020). "The immunoregulatory roles of NCF1 have also been studied in experimental autoimmune encephalomyelitis (EAE), which is a widely accepted model to study multiple sclerosis (MS)." (PMID 32276661, 2020).
Alzheimer disease (4 papers, 2022 to 2025). A progressive, neurodegenerative disease characterized by loss of function and death of nerve cells in several areas of the brain leading to loss of cognitive function such as memory and language. "Finally in M_SC4, increased expression of Ncf1/p47phox has been reported in phagocytic microglia and upregulation of Tyrobp and Trem2 (a M_SC4 top marker gene) are known markers for DAMs, Alzheimer’s disease-associated microglia with phagocytic activity." (PMID 37293629, 2023).
Coronary Heart Disease (4 papers, 2017 to 2024). "Two proteins (PCSK9 and AIDA) exhibited associations with HF in patients with coronary heart disease (CHD), and four proteins (PCSK9, SWAP70, NCF1, and RELT) were related with HF in patients receiving antihypertensive medication." (PMID 38383373, 2024). "Our study identified two proteins, PCSK9 and AIDA, linked to HF in patients with coronary heart disease (CHD), and four proteins, PCSK9, SWAP70, NCF1, and RELT, associated with HF in patients receiving antihypertensive medication." (PMID 38383373, 2024).
inflammatory bowel disease (4 papers, 2008 to 2025). A spectrum of small and large bowel inflammatory diseases of unknown etiology. "Two recent studies have reported that less copies of NCF1 pseudogenes may produce more reactive oxygen intermediates and may exaggerate certain diseases involving inflammatory process such as inflammatory bowel disease." (PMID 20178640, 2010).
lung carcinoma (4 papers, 2011 to 2024). "In summary, SMC6, CDC27, CDC7, RACGAP1, SMC4, NCF1,2,4, SELPLG and CFP are significantly associated with T2DM and lung cancer, making them potential target genes for disease prediction and treatment in the future." (PMID 38468345, 2024). "The expressions of EMR3, NCF1, CSF2RB, DYSF, TLR8, and HCK in the lung cancer group were significantly different from those of the control group." (PMID 35923697, 2022).
pneumonia (4 papers, 2006 to 2025). An acute, acute and chronic, or chronic inflammation focally or diffusely affecting the lung parenchyma, caused by an infection in one or both of the lungs (by bacteria, viruses, fungi, or mycoplasma.). "Furthermore, neutrophil cytosolic factor 1 (NCF1) encodes for a component of the NADPH oxidase complex and has been associated with fibrosis, inflammation, as well as pneumonia." (PMID 35903362, 2022).
asthma (3 papers, 2021 to 2022). "We therefore tested the effect of a Ncf1 mutation, prohibiting a functional ROS response, using the classic antigen induced pulmonary inflammation, often used as a mouse model for human asthma." (PMID 34970267, 2021). "Due to the limitation of experimental conditions, we did not analyze the lung function, limiting us to fully understand the role of Ncf1 in asthma pathogenesis." (PMID 34970267, 2021). "However, the role of Ncf1 in the pulmonary inflammatory diseases like asthma remains unknown." (PMID 34970267, 2021). "The levels of most proteins (ITGAM, ITGB2, MMP12, NCF1, NCF2, NCF4, RAC2 and Vav1) were higher in the asthma condition (shown in red) than those in the control condition or after SCIT condition." (PMID 34618857, 2021). "The role of Ncf1 in HDM animal model and human asthma will be our prior focus in the future." (PMID 34970267, 2021).
colorectal cancer (3 papers, 2014 to 2024). A primary or metastatic malignant neoplasm that affects the colon or rectum. "Furthermore, a longer five-year survival rate for colorectal cancer patients correlated with a higher expression of NCF4, but not NCF1 or NCF2." (PMID 38886341, 2024).
depression (3 papers, 2020 to 2022). "For the first time, we discovered that NCF1 and CYBA might be key target genes that explain the role of ERS in the pathogenesis of depression." (PMID 36353576, 2022).
lymphoma (3 papers, 2013 to 2025). A malignant (clonal) proliferation of B- lymphocytes or T- lymphocytes which involves the lymph nodes, bone marrow and/or extranodal sites. "WES revealed significantly mutated genes, including several known (NCF1, MMP9, and VDR) and possibly other candidate (CNN2, MUC4, MTSS2, KMT2C, HAVCR2, and TCF19) genes, most of which were associated with the physiological activation of lymphoma cells." (PMID 41296384, 2025). "Besides, NCF1 protein was significantly downregulated (p<0.005) in cHL compared to other lymphoma cell lines." (PMID 24376854, 2013).
multiple sclerosis (3 papers, 2008 to 2025). A progressive autoimmune disorder affecting the central nervous system resulting in demyelination. "This study examined for the first time a possible influence of type I/type II NCF1 pseudogene ratios on ROI production and disease severity in children with malaria and susceptibility to multiple sclerosis in a German and Polish population." (PMID 19077231, 2008).
Obesity (3 papers, 2014 to 2022). Accumulation of substantial excess body fat. "The positive correlation with expression of NCF-1 of the NADPH oxidase system may relate to its regulation by MCP-1 and priming of NADPH oxidase by IL-8, contributing to systemic oxidative stress in clinical obesity." (PMID 34371884, 2021).
primary immunodeficiencies (3 papers, 2022 to 2024). "Another patient had primary immunodeficiency disease (autosomal recessive chronic granulomatous disease type 1 with a homozygous pathogenic variant identified in the NCF1 gene)." (PMID 36517065, 2022). "In comparisons to both healthy controls and other primary immunodeficiencies (PIDs) including NCF1/NCF2 mutant CGD, we defined the gp91 expression level in patients with X91+ as > 70%, X91− as 5–70%, and X910 as < 5%." (PMID 35796921, 2022).
tuberculosis (3 papers, 2006 to 2025). A chronic, recurrent infection caused by the bacterium Mycobacterium tuberculosis. "This study aims to investigate the relationship between the NCF1 Arg90His variation and susceptibility to tuberculosis." (PMID 39917298, 2025). "To test this hypothesis, we investigated whether the NCF1 rs201802880 variant offers a protective effect against tuberculosis (TB), a historically significant and deadly infectious disease." (PMID 39917298, 2025). "To assess the hypothesis that the NCF1 rs201802880 AA genotype offers protection against tuberculosis, we genotyped all 492 TB patients and 490 controls for this polymorphism." (PMID 39917298, 2025).
alcoholic hepatitis (2 papers, 2022 to 2023). Acute hepatitis resulting from ingestion of alcohol. "RNA-Seq analysis and the data from experimental models revealed that neutrophilic NCF1-dependent ROS promoted alcoholic hepatitis (AH) by inhibiting AMP-activated protein kinase (a key regulator of lipid metabolism) and microRNA-223 (a key antiinflammatory and antifibrotic microRNA)." (PMID 35838051, 2022).
Cirrhosis (2 papers, 2018 to 2019). A chronic disorder of the liver in which liver tissue becomes scarred and is partially replaced by regenerative nodules and fibrotic tissue resulting in loss of liver function. "Because neutrophils from patients with decompensated cirrhosis exhibit decreased mTOR protein, this has been suggested to result in reduced translation of NCF1 into p47phox in these cells as well-translation of gp91phox." (PMID 31134093, 2019).
Crohn disease (2 papers, 2018 to 2025). A gastrointestinal disorder characterized by chronic inflammation involving all layers of the intestinal wall, noncaseating granulomas affecting the intestinal wall and regional lymph nodes, and transmural fibrosis. "Reduced NCF1 expression is also associated with more frequent flares in patients with Crohn’s disease." (PMID 40710296, 2025).
enthesitis (2 papers, 2018 to 2022). Inflammation at the site of insertion of ligaments, tendons, and other fibrous structures into bone. "Enthesitis was induced by local injection of monosodium urate (MSU) crystals into the metatarsal entheses of wild-type (WT) or oxidative-burst-deficient (Ncf1**) mice." (PMID 30045841, 2018). "Areas of erosions were detected at late stages of chronic enthesitis of Ncf1** mice using CT analysis and were found in the enthesiophytes as well as in the original cortical bone layer." (PMID 30045841, 2018). "While the numbers of CD31+ vessels were not increased in the inflammatory tissue between the metatarsals, we found elevated numbers of proliferating CD31-positive vessels in the cavities of newly formed enthesiophytes of Ncf1** mice during chronic enthesitis." (PMID 30045841, 2018). "To validate local angiogenesis in enthesitis, we performed histological analysis of paw sections from WT and Ncf1** mice 21 days after disease onset." (PMID 30045841, 2018). "For assessing vascularization in spurious and chronic enthesitis, we performed dynamic contrast-enhanced (DCE)-MRI in MSU-crystal-injected WT and Ncf1** mice, respectively." (PMID 30045841, 2018). "While injection of MSU crystals into WT mice triggered transient mild enthesitis with no new bone formation, Ncf1** mice developed chronic enthesitis accompanied by massive enthesiophytes." (PMID 30045841, 2018). "The combination of inflammation with new bone formation only in Ncf1** mice suggests rapid pathologic bone turnover in conjunction with chronic but not acute enthesitis." (PMID 30045841, 2018).
malaria (2 papers, 2008 to 2014). Malaria is a serious and sometimes fatal disease caused by a parasite that commonly infects a certain type of mosquito which feeds on humans. "This study evaluates whether NCF1 ΔGT/GTGT ratios are associated with severity of Plasmodium falciparum malaria or individual ROI production in Gabonese children suffering from malaria." (PMID 19077231, 2008). "The genomic pattern of NCF1 and its pseudogenes might influence ROI production but only marginally influence susceptibility to and outcome of malaria and MS." (PMID 19077231, 2008).